LRRN2 (leucine rich repeat neuronal 2)
Synonyms: GAC1; LRRN5; LRANK1; FIGLER7
Tractability: Antibody: UniProt predicts a signal peptide or a membrane-spanning region; its Gene Ontology location is reachable by antibodies, with medium confidence.
Gene: Protein-coding gene on chromosome 1 (204,617,170 to 204,685,738, reverse strand). Ensembl gene ENSG00000170382.
Subcellular location: Membrane
Subcellular location (Human Protein Atlas): Endoplasmic reticulum
Gene Ontology:
Molecular function: signaling receptor activity
Biological process: cell adhesion; signal transduction
Cellular component: plasma membrane; membrane
Genetic constraint (gnomAD): Loss-of-function variants: 14 observed, 42.39 expected, observed/expected ratio (o/e) 0.33, 90% interval 0.22 to 0.52. The upper end of that interval is the gene's LOEUF score, 0.52, which puts it in group 2 of 6, group 1 being the genes least tolerant of losing a copy. Missense variants: 731 observed, 983.15 expected, observed/expected ratio (o/e) 0.74, 90% interval 0.7 to 0.79. Synonymous variants: 391 observed, 430.39 expected, observed/expected ratio (o/e) 0.91, 90% interval 0.83 to 0.99.
Homologues: Orthologues: chimpanzee LRRN2 (99% identical), macaque LRRN2 (99% identical), pig LRRN2 (95% identical), guinea pig LRRN2 (90% identical), rabbit LRRN2 (90% identical), mouse Lrrn2 (90% identical), rat Lrrn2 (89% identical). Paralogues in human: LRRN1 (47% identical), LRRN3 (46% identical), SLIT3 (21% identical), SLIT1 (21% identical), LRFN3 (20% identical), SLIT2 (20% identical), LRFN4 (20% identical), LINGO1 (20% identical), LINGO2 (20% identical), LRFN1 (20% identical), TLR9 (19% identical), LRFN5 (19% identical), and 13 more.
Diseases named in the same sentence as LRRN2 in open-access papers:
LRRN2 is named in the same sentence as 11 diseases in open-access papers, as found by Europe PMC text mining. Sharing a sentence is not in itself a finding about the gene and the disease. The quoted sentences say what the papers report.
Alzheimer disease (2 papers, 2019 to 2021). A progressive, neurodegenerative disease characterized by loss of function and death of nerve cells in several areas of the brain leading to loss of cognitive function such as memory and language. "The nuclear hub network enrichment was driven by genes implicated in Alzheimer’s disease (APOE), non-alcoholic drug-related phenotypes (RAB4B-EGLN2), and cognitive ability (LRRN2 and MAPT)." (PMID 31171808, 2019).
glioma (2 papers, 2016 to 2022). A benign or malignant brain and spinal cord tumor that arises from glial cells (astrocytes, oligodendrocytes, ependymal cells). "LRRN2 was the first to be reported upregulated in glioma and was related to cell adhesion and signal transduction." (PMID 35464857, 2022).
breast carcinoma (1 paper, 2025). "In contrast, LRRN2 showed marked overexpression in breast cancer specimens." (PMID 41458604, 2025). "The observed differential expression patterns, particularly the consistent downregulation of LRRN1, LRRN3, and LRRN4CL coupled with LRRN2 upregulation, prompted us to focus our subsequent investigations on elucidating the specific mechanisms of these proteins in breast cancer metastasis." (PMID 41458604, 2025).
tumor (5 papers, 2013 to 2025). "MDM4 is expressed in breast tissue and is amplified and overexpressed along with LRRN2 and PIK3C2B in breast and other tumor types (TCGA)." (PMID 23544013, 2013). "In contrast to LRRN1’s expression profile, LRRN2 exhibited significant upregulation in cancer tissues, though its associations with AJCC stage and tumor size showed only marginal trends without statistical significance." (PMID 41458604, 2025). "In the HPA data, compared with normal tissues, DHRS13, PLEKHH1were expressed at medium to high levels in tumor tissues, while the expression of PSMB9, and LRRN2 was significantly up-regulated in OC samples, and AMMECR1, KIAA0100 slightly downregulated in OC samples." (PMID 36307842, 2022).
LRRN2 also shares sentences with these, for which no sentence is quoted: cancer (2 papers); brain tumors (1); ependymoma (1); Insulin resistance (1); lung adenocarcinoma (1); malignant glioma (1); Sepsis (1).